ALK (ALK receptor tyrosine kinase)
Diseases named in the same sentence as ALK in open-access papers (continued):
Sharing a sentence is not in itself a finding about the gene and the disease.
non-small cell lung carcinoma (continued). "In the last decade, the approval of immune checkpoint inhibitors (ICIs), such as anti-PD-1/PD-L1, has improved survival and long-term responses in patients with non-small cell lung cancer (NSCLC) without anaplastic lymphoma kinase (ALK) or epidermal growth factor receptor (EGFR) driver mutations." (PMID 39596334, 2024). "HCC827 (EGFR mutated non-small-cell lung cancer: NSCLC) and H3122 (ALK+ NSCLC) cells did not respond to the FM, whereas SKBR3 (HER2+ breast cancer), BT474 (HER2+ breast cancer), and HCT116 (colorectal cancer) cells were responsive to it, showing reduced cell viability." (PMID 38999849, 2024). "The College of American Pathologists and the Association of Molecular Pathology guidelines recommend EGFR, ALK and ROS1 gene tests as mandatory in non-small cell lung carcinoma(NSCLC)." (PMID 35446881, 2022). "Immunotherapy (IO), in the form of immune checkpoint inhibitors (ICI), is the standard first-line (1L) therapy in patients affected by non-small cell lung cancer (NSCLC) without epidermal-growth factor receptor (EGFR) or anaplastic lymphoma kinase (ALK) gene alterations." (PMID 36033444, 2022). "In support of the efficacy of homogenization therapy, a case study of a patient with ALK-rearranged non-small-cell lung cancer (NSCLC) has been described, where the authors postulated that cells exhibited unique, temporally restricted collateral sensitivities during adaptation to ALK inhibition." (PMID 35603167, 2022). "For instance, in non-small cell lung cancer patients with no available tumor biopsy, blood is the only source for detecting genetic alterations, including EGFR, KRAS, BRAF, PIK3CA mutations, and ALK rearrangements." (PMID 34359285, 2021). "RET kinase domain fusion with kinesin family member 5B was identified in about 1–2% of patients with non-small-cell lung cancer (NSCLC), who were negative for mutations or rearrangements in other common oncogenic drivers such as EGFR, HER, ERBB2, BRAF, KRAS, ALK, etc.." (PMID 32993133, 2020). "A study revealed that pembrolizumab monotherapy has shown significant improvements in overall survival as a first-line treatment compared with conventional chemotherapy for locally advanced or metastatic non-small-cell lung cancer without sensitising EGFR or ALK alterations when PDL1 TPS ≥ 1%." (PMID 32587640, 2020). "In contrast, as another example, crizotinib significantly improved patients in the subgroup under a clinical trial in which only biomarker-positive patients with advanced anaplastic lymphoma kinase (ALK)-positive nonsquamous non-small cell lung cancer (NSCLC) were set as the targeted population." (PMID 31331277, 2019). "Furthermore, one of the non-small cell lung cancer fusion gene, EML4-ALK, which activates ALK kinase and contributes to poor prognosis, derives from the circRNA-circ F-EA, which can be detected in the plasma of patients who harbored the EML4-ALK fusion gene." (PMID 31511040, 2019). "ALK and EGFR tyrosine-kinase inhibitors showed better activity and efficacy than standard chemotherapy in the first and second line treatment settings, leading to a clear advantage in overall survival of advanced non-small cell lung cancer patients harboring these genetic alterations." (PMID 28938691, 2017). "Anaplastic lymphoma kinase (ALK) rearrangements, which are generally associated with pulmonary adenocarcinomas in female non-smokers, occur in approximately 5% of patients with non-small cell lung cancer (NSCLC)." (PMID 24499728, 2014). "Accordingly, crizotinib, an FDA-approved drug used for the treatment of patients with ALK-positive and ROS1-positive non-small cell lung carcinoma (NSCLC), triggered the nuclear translocation of FOXO3 suggesting an important role of RTKs such as ALK, MET or ROS1 in the regulation of FOXO3." (PMID 36080182, 2022).
non-small cell lung carcinoma (continued). "In conclusion, the genetic mutations associated with PACC are different from those implicated in non-small cell lung cancer, and EGFR, KRAS, BRAF, ALK, PIK3CA, PDGFRA, and DDR2 may not be driver genes in PACC; we must identify other genes for targeted therapy against PACC." (PMID 26373952, 2015). "Several studies have reported that ALK or MET over-expression and constitutive kinase activation correlate with advanced stage and may be predictive of poor clinical outcome in several neoplasia, such as neuroblastoma, gastrointestinal carcinoma and non-small-cell lung cancer." (PMID 26445453, 2015). "Patients with advanced non-small cell lung cancer and programmed cell death-ligand 1 expression ≥50% received cemiplimab monotherapy (n=283), and patients with no EGFR, ALK, or ROS1 genomic aberrations received cemiplimab plus chemotherapy (n=312)." (PMID 41194933, 2025). "Immune checkpoint blockade that activates CD8 + T cells is the standard of care for patients with metastatic non-small cell lung cancer (NSCLC) lacking actionable genomic alterations (such as EGFR and ALK alterations)." (PMID 40849493, 2025). "Conversely, in anaplastic lymphoma kinase-negative anaplastic large cell-lymphoma (ALK-negative ALCL) and non-small cell lung cancer MIR503HG is upregulated and mediates tumor-promoting effects." (PMID 39676172, 2024). "There were two cases of BRAF mutation other than V600E, comprising 0.5% of all non-small cell carcinoma, 0.8% of adenocarcinoma and non-small cell carcinoma without EGFR/ALK aberrations and 1.5% of adenocarcinoma without EGFR/ALK aberrations." (PMID 37374289, 2023). "Health Canada approved pembrolizumab in the first-line setting for advanced non-small-cell lung cancer with PD-L1 ≥ 50% and no EGFR/ALK aberration." (PMID 37366902, 2023). "For patients with advanced non-small-cell lung cancer (NSCLC) without targetable oncogene alterations (EGFR, ALK, ROS-1, etc.), chemotherapy used to be the best first-line treatment." (PMID 35237263, 2022). "Molecular analysis of NTRK fusion-positive non-small-cell lung cancers showed no concurrent alterations in KRAS, EGFR, ALK, and ROS1 or other known oncogenic drivers." (PMID 34531526, 2022). "First-line treatment for patients with metastatic or recurrent non-small cell lung cancer (NSCLC), with no epidermal growth factor receptor (EGFR) or anaplastic lymphoma kinase (ALK) genomic tumor aberrations." (PMID 35037899, 2022). "Pretherapeutic cancer samples of 122 patients [86 non-small cell lung cancer and 36 small cell lung cancer (SCLC)] harboring no EGFR/ALK alterations were collected." (PMID 34604048, 2021). "An early analysis of 1073 non-small cell lung cancer (NSCLC) specimens demonstrated no overlap between ROS1 and ALK rearrangements." (PMID 29455670, 2018). "Platinum-based chemotherapy is currently the first-line treatment of choice for patients with advanced non-small-cell lung cancer (NSCLC) in the presence of wild-type epidermal growth factor receptor and non-rearranged ALK." (PMID 27179511, 2016). "In addition, ALK fusion proteins have been reported in nonelastic ALCL, inflammatory myofibrosarcoma (IMT), diffuse large B-cell lymphoma (DLBCL), and non-small cell lung cancer (NSCLC)." (PMID 37375228, 2023). "In non-small-cell lung cancer (NSCLC), multiple nonhistone proteins are modified by SMYD2 mediated methylation, and effects on tumors are generated by the modified activity of signaling pathways, for example, MAPKAPK3 in PDAC and ALK." (PMID 36520265, 2022). "However, the antibodies we applied here are widely used in routine; Total ALK antibody (D5F3) was well validated in previous studies not only for MCC but also for other cancers such as non-small-cell lung carcinoma." (PMID 34029351, 2021).
anaplastic large cell lymphoma (806 papers, 2006 to 2026). Anaplastic large cell lymphoma (ALCL) is a rare and aggressive peripheral T-cell non-Hodgkin lymphoma, belonging to the group of CD30-positive lymphoproliferative disorders, which affects lymph nodes and extranodal sites. "ML162 (a GPX4 inhibitor) treatment in FDFT1‐deficient ALK+ ALCL (ALK+ anaplastic large cell lymphoma) cells depleted squalene, damaging membrane PUFAs, key ferroptosis drivers, and generating lipid peroxides that induced ferroptosis." (PMID 40145543, 2025). "The Anaplastic Lymphoma Kinase (ALK) gene was originally identified in 1994 and implicated in the development of a particular type of cancer, anaplastic large cell lymphoma." (PMID 41213866, 2025). "The ALK gene, which was initially identified in 1994 by Morris from anaplastic large cell lymphoma (ALCL), encodes a receptor tyrosine kinase (RTK) belonging to the highly conserved insulin receptor superfamily." (PMID 40246819, 2025). "Anaplastic large cell lymphomas (ALCLs) are mature T-cell lymphomas classified into ALK-positive, ALK-negative, and breast implant-associated ALCLs." (PMID 41395560, 2025). "In line with this, loss of SQLE is the cause of the cholesterol auxotrophy in ALK+ anaplastic large cell lymphoma (ALCL) cell lines." (PMID 39349433, 2024). "Numerous fusion partners of ALK have been identified (e.g., nucleophosmin (NPM)-ALK in anaplastic large cell lymphoma (ALCL) and echinoderm microtubule-associated protein-like 4 (EML4)-ALK in non-small cell lung cancer (NSCLC))." (PMID 37954850, 2023). "Various rearrangements (fusions), mutations, amplification, and alternative splicing of the ALK gene have been found in anaplastic large cell lymphoma (ALCL), inflammatory myofibroblastoma (IMT), non-small cell lung cancer (NSCLC), and other human tumors." (PMID 35958559, 2022). "Anaplastic lymphoma kinase (ALK) is a tyrosine kinase associated with Anaplastic Large Cell lymphoma (ALCL) through oncogenic translocations mainly NPM-ALK." (PMID 33466277, 2021). "Studies in nucleophosmin-anaplastic lymphoma kinase (NPM-ALK) positive (ALK+) T-cell lymphoma, a subgroup of anaplastic large cell lymphoma (ALCL), have implicated the transcription factor STAT3 as a central player in epigenetic regulation." (PMID 33310759, 2021). "The ALK gene has been found to be rearranged, mutated, or amplified in a series of tumors, including anaplastic large cell lymphoma, neuroblastoma, and non-small-cell lung cancer (NSCLC)." (PMID 34530849, 2021). "Anaplastic large cell lymphomas associated with ALK translocation have a good outcome after CHOP treatment; however, the 2-year relapse rate remains at 30%." (PMID 34771686, 2021). "With the exception of the ALK-positive anaplastic large cell lymphoma (ALCL) subtype, nodal PTCLs are generally associated with a poor prognosis, with a 5-year survival of approximately 30%." (PMID 32225002, 2020). "The anaplastic lymphoma kinase (ALK) gene, that was discovered in 1994 in anaplastic large cell lymphoma (ALCL), encodes a transmembrane receptor tyrosine kinase, whose alteration leads to constitutive ALK activation and generates oncogenic activity." (PMID 37362555, 2020). "The NPM1-ALK (anaplastic lymphoma kinase) fusion protein is the hallmark of ALK-positive anaplastic large cell lymphoma." (PMID 29855342, 2018). "A Phase 1 study of crizotinib in pediatric patients with refractory solid tumors or anaplastic large-cell lymphoma showed that the regimen was tolerable and warranted further investigation in neuroblastoma patients with ALK oncogenic mutations." (PMID 30154341, 2018). "With the exception of low-risk anaplastic lymphoma kinase (ALK)-positive anaplastic large cell lymphoma (ALCL), the majority of patients relapse rapidly; the current 5-year overall survival rates are only 10–30 %." (PMID 27071634, 2016). "The first ALK mutation was reported in 1994 when NPM-ALK was described in a subset of anaplastic large cell lymphomas." (PMID 26951079, 2016).
anaplastic large cell lymphoma (continued). "The ALK gene fusion was originally identified in anaplastic large cell lymphoma and encodes a cell surface tyrosine kinase that serves as a potential therapeutic target." (PMID 27213405, 2016). "Constitutive STAT3 activation and loss of SHP-1 in ALK-positive anaplastic large cell lymphoma have provided an example of a positive feedback loop." (PMID 24995504, 2014). "Expression of anaplastic lymphoma kinase (ALK) fusion proteins resulting from chromosomal translocations involving chromosome band 2p23 is a hallmark of anaplastic large cell lymphomas (ALCL)." (PMID 21494621, 2011). "Genetic alterations involving ALK, including gene fusions, amplification, and mutations, have been identified in anaplastic large cell lymphomas, inflammatory myofibroblastic tumors, and neuroblastoma, respectively." (PMID 20624322, 2010). "Surgical excision and biopsy revealed a dense dermal and subcutaneous infiltrate of large atypical lymphoid cells with strong and diffuse CD30 expression (~80%-90% of tumor cells), CD4 positivity, ALK-negativity, and loss of pan-T-cell markers, consistent with anaplastic large cell lymphoma (ALCL)." (PMID 42017675, 2026). "The first clinical trial with crizotinib in children suggested that inhibition of mutated ALK in neuroblastoma may be more difficult to achieve compared to inhibition of ALK fusions such as the NPM-ALK fusion in anaplastic large-cell lymphomas." (PMID 31452835, 2019). "Additionally, one novel truncated form of an ALK variant (ALK Δ2–17) was identified recently in a ALK-positive anaplastic large cell lymphoma and one synovial sarcoma cell line." (PMID 30400214, 2018). "Alterations in ALK gene including chromosomal translocations, mutations, and overexpression have been implicated in the development of ALK-positive human cancers including anaplastic large cell lymphomas (ALCL) and non-small cell lung cancers (NSCLC)." (PMID 28806414, 2017). "In addition, constitutively activated ALK causes increased VEGF secretion in anaplastic large-cell lymphoma." (PMID 28837676, 2017). "As suggested by its name, ALK was first described as part of a translocation product in cases of anaplastic large-cell lymphoma, with other genetic and cytogenetic ALK mutations subsequently coming to attention in the development of many other hematologic and solid organ malignancies." (PMID 28895885, 2017). "Moreover, ALK fusion genes are associated with both anaplastic large-cell lymphoma and inflammatory myofibroblastic tumors." (PMID 27598116, 2016). "Interestingly, loss of SHP-1 in ALK-positive anaplastic large cell lymphoma is a direct consequence of the constitutive activation of STAT3 in these cells, as STAT3 plays a key role in promoting gene methylation and silencing of SHP1." (PMID 24995504, 2014). "Conversely, ALK mutations or translocations, particularly in ALK-positive anaplastic large cell lymphoma (ALCL), are associated with a distinct clinical and biological profile." (PMID 40191738, 2024). "Anaplastic large cell lymphoma (ALCL), the most common T-cell pediatric lymphoma, has an active pathogenic ALK oncogene and shows a high level of cell surface expression of CD30." (PMID 33916177, 2021). "Anaplastic large cell lymphomas are T cell lymphomas which include ALK+ ALCL, ALK- ALCL, cutaneous ALCL, and breast implant-associated ALCL." (PMID 33413671, 2021). "Direct activation of STAT3 by the NPM-ALK chimeric protein, which plays a central pathogenic role in anaplastic large cell lymphoma (ALCL), promotes invasiveness of ALK-positive ALCL through induction of Twist-1." (PMID 31952344, 2020). "Twenty different ALK-fusion proteins that result from various chromosomal rearrangements have been identified, and they have been implicated in the pathogenesis of several diseases including anaplastic large-cell lymphoma, diffuse large B-cell lymphoma, and inflammatory myofibroblastic tumors." (PMID 30820191, 2019).
anaplastic large cell lymphoma (continued). "Most cases of anaplastic lymphoma kinase-positive (ALK+) anaplastic large cell lymphoma (ALCL) exhibit a common anaplastic morphology with hallmark cells." (PMID 29952979, 2018). "Moreover, MiR-342-3p expression associated the CD3+ T-cells in ALK- anaplastic large cell lymphoma." (PMID 29731996, 2018). "Perhaps the best human correlate with this mouse model is anaplastic large cell lymphoma (ALCL), a T-cell lymphoma characterized by activating mutations of anaplastic large cell kinase (ALK)." (PMID 28881594, 2017). "ATIC-ALK fusion mutations are very rare, comprising approximately 1% of ALK-fusion mutations in anaplastic large cell lymphomas (ALCL)." (PMID 27846861, 2016). "Compared to the general population, the relative survival rate was highest in anaplastic lymphoma kinase (ALK)-positive anaplastic large cell lymphoma." (PMID 40839148, 2025). "Subgroup analysis showed that only anaplastic lymphoma kinase (ALK)-positive anaplastic large-cell lymphoma (ALCL) patients benefited from the CHOPE regimen." (PMID 40556671, 2025). "The oncogenic ALK can be activated by ALK fusions in several cancers, such as NSCLC, anaplastic large cell lymphoma (ALCL), as well as by point mutations in neuroblastoma and anaplastic thyroid cancer." (PMID 40234387, 2025). "While anaplastic lymphoma kinase (ALK) gene fusion was seen in large-cell lymphomas, its fusion with the promoter gene, echinoderm microtubule-associated protein-like 4 (EML4), was first discovered in 2007 in NSCLC as an oncogenic driver alteration." (PMID 39941723, 2025). "PTCL, NOS is the second most frequent mature T-cell lymphoma in children after anaplastic large-cell lymphoma, ALK positive (ALCL, ALK +)." (PMID 39707053, 2025). "Background/Objectives: Anaplastic lymphoma kinase (ALK)-positive (+) anaplastic large cell lymphoma (ALCL) is known to express CD25, but its significance has not been well studied." (PMID 40507248, 2025). "Specifically, excluding ALK-positive anaplastic large cell lymphoma, the overall prognosis for patients with PTCL is generally poor, as approximately only 30% of patients achieve cure following initial treatment." (PMID 41394820, 2025). "It is noteworthy that such genetic alterations are more commonly observed in ALK-negative anaplastic large cell lymphoma (ALK-ALCL) but are less commonly reported in ALK+ALCL." (PMID 41584605, 2025). "The negativity of PSA and CK further excluded a prostatic or epithelial origin, while the negativity of CD3, CD30, and ALK1 ruled out other hematopoietic malignancies such as T‐cell lymphomas or ALK‐positive large cell lymphoma." (PMID 40438750, 2025). "Anaplastic large cell lymphoma (ALCL) is a heterogeneous subtype of T‐cell lymphoma usually driven by genetic alterations affecting the anaplastic lymphoma kinase (ALK) gene." (PMID 40734623, 2025). "Histopathological evaluation revealed ALK positivity, consistent with the anaplastic large cell lymphoma subtype, which is rare and more aggressive compared to the other subtypes." (PMID 40024178, 2025). "Primary central nervous system (CNS) T-cell lymphomas, such as anaplastic large-cell lymphoma (ALCL) with anaplastic lymphoma kinase (ALK) negativity, are relatively rare and aggressive." (PMID 40777017, 2025). "Anaplastic lymphoma kinase positive (ALK+) anaplastic large cell lymphoma (ALCL) typically affects young individuals and, despite high responsiveness to cytotoxic drugs, relapses occur in over 50% of patients." (PMID 39809726, 2025). "A notable example is the NPM (nucleophosmin)-ALK fusion gene, frequently identified in anaplastic large cell lymphoma." (PMID 40584293, 2025).